SEMA4D (semaphorin 4D)
Diseases named in the same sentence as SEMA4D in open-access papers (continued):
Sharing a sentence is not in itself a finding about the gene and the disease.
psoriasis (8 papers, 2020 to 2026). An autoimmune condition characterized by red, well-delineated plaques with silvery scales that are usually on the extensor surfaces and scalp. "Researchers found out that the serum level of Sema4D is elevated in psoriasis patients and that the expression of Sema4D and its receptor PlexinB2 is increased in keratinocytes of psoriatic lesions." (PMID 38139064, 2023). "The study revealed a negative regulatory mechanism for dendritic cells in psoriasis through Sema4D-PlexinB2." (PMID 38139064, 2023). "The expression of PlexinB2 on keratinocytes is increased in the lesional skin of psoriasis patients, and the levels of Sema4D are elevated in sera of psoriasis patients and on keratinocytes of psoriatic skin." (PMID 38139064, 2023). "That also confirms the fact that the expression level of PlexinB2 on dendritic cells from peripheral blood of psoriasis patients was lower than that on healthy individuals and that Sema4D inhibited the production of pro-inflammatory cytokines by dendritic cells." (PMID 38139064, 2023). "This specific targeting of Sema4D-PlexinB2 might be developed as a therapeutic strategy for the treatment of psoriasis." (PMID 38139064, 2023). "Another semaphorin which might have an impact on psoriasis etiopathogenesis is Sema4D (also known as CD100)." (PMID 38139064, 2023). "Sema4D was also suggested to induce keratinocyte mediated inflammatory responses in psoriasis." (PMID 35054504, 2022).
leukemia (7 papers, 2007 to 2024). A malignant (clonal) hematologic disorder, involving hematopoietic stem cells and characterized by the presence of primitive or atypical myeloid or lymphoid cells in the bone marrow and the blood. "Sema3A and Sema4D were furthermore similarly implicated in leukemia cell regulation." (PMID 33537086, 2021). "Previously, semaphorin 4D was linked to the activation of the PI3K/AKT and ERK signaling pathways, which would lead to the development of leukemia cells." (PMID 39200388, 2024). "Noteworthy, current data support a promoting role for Semaphorin 4D and Neuropilin-1 in these tumors, while Semaphorin 3A seems to consistently act as oncosuppressor in leukemias and multiple myeloma." (PMID 31143707, 2019). "It is assumed that Sema4D plays a crucial role in leukemia development by regulating the PI3k/AKT and ERK signaling pathways and may be a biomarker for ALL prognosis." (PMID 37627214, 2023). "Semaphorin 4D (Sema4D) is highly expressed in various cancers and leukemia." (PMID 35401878, 2022). "Consistent with the posited tumor suppressor role of this semaphorin, experimental studies ex vivo have shown that Sema3A can suppress the growth and promote the apoptosis of human leukemic cells, via diverse mechanisms; Sema4D, in contrast, was found to promote leukemia cell survival and growth." (PMID 33537086, 2021). "Thus, multiple data support a pro-tumorigenic role of SEMA4D in leukemias, consistent with the current knowledge about this semaphorin in solid tumors." (PMID 31143707, 2019). "In sum with reference to leukemias, SEMA4D could be a promising therapeutic target also for the treatment of multiple myeloma." (PMID 31143707, 2019). "As blasts mainly exist in the bone marrow in healthy people but not in peripheral blood, high Sema4D levels in serum may indicate infiltration and proliferation of leukemia cells in peripheral blood." (PMID 35401878, 2022).
melanoma (7 papers, 2007 to 2024). A malignant, usually aggressive tumor composed of atypical, neoplastic melanocytes. "Through a combination of molecular biology techniques and in silico analysis, the role of Sema4D in improving anti-PD-L1 sensitivity in melanoma was explored." (PMID 37096066, 2023). "In this study, we use a combination of molecular biology techniques and bioinformatics to explore the roles of Sema4D in anti-PD-1 resistance melanoma." (PMID 37096066, 2023). "Sema4D is upregulated in most tumor tissues, such as prostate, colon, breast, melanoma, head, and neck carcinomas." (PMID 37096066, 2023). "Sema4D expressed on many cancer cells, Plexin-B1 also expression in cancer such as ovarian, melanoma, when Sema4D combined with Plexin-B1, it correlates with tumor immune infiltration, angiogenesis, and tumor progression in melanoma." (PMID 37096066, 2023). "Of note, the evidence that Sema4D, together with Sema6A, is the most expressed protein in melanoma, being expressed in 100% of melanoma tissues." (PMID 33858502, 2021). "Sema4D expression in melanoma cells was detected using clone 30 antibody (BD-Transduction lab), by immunopurification and Western blotting experiments according to standard protocols." (PMID 17519029, 2007). "This study intends to elucidate that Sema4D may be involved in the sensitivity of melanoma to nivolumab therapy via PI3K/AKT signaling pathway." (PMID 37096066, 2023). "We demonstrated for the first time that Sema4D is involved in anti-PD-1 resistance in melanoma." (PMID 37096066, 2023). "Then, we identified 9 LR pairs (“BMP6- > HJV” 、"CCL8- > ACKR4” 、"DLL3- > NOTCH3"、"DSC3- > DSG3"、"GHRH- > GHRHR” 、"LRRC4B- > PTPRF"、"SEMA4D- > PLXNB1"、"SFRP1- > FZD6"、"UCN- > CRHR1′′) as key LR pairs in melanoma prognosis through Lasso Cox regression and Multiple Stepwise Regression." (PMID 36777724, 2023). "The role of Sema4D in melanoma with anti-PD-1 resistance is poorly understood." (PMID 37096066, 2023). "Therefore, we provide the evidence for the first time that Sema4D and Plexin-B1 is related to anti-PD-1 resistance of melanoma." (PMID 37096066, 2023). "Finally, we tested the effect of nivolumab on Sema4D-knockdown melanoma in mice." (PMID 37096066, 2023). "EPHB6 was down-regulated in several cancer types such as metastatic lung cancer, melanoma, and CRC, while high expression of SEMA4D promoted angiogenesis in many tumors." (PMID 37182141, 2023). "The results showed that the expression of DSC3, DLL3, BMP6, SEMA4D, and GHRH are increased (p < 0.05) in melanoma, while the expression of LRRC4B, SFRP1, DCN, and CCL-8 decreased in melanoma (p < 0.05)." (PMID 36777724, 2023). "Results from the immunohistochemistry assay revealed that SEMA4D and IFITM1 were down-regulated, while KIF20A and GPR87 were over-expressed in melanoma tissue." (PMID 34659201, 2021). "When analyzing the potential biological functions of these proteins in melanoma, we found that silencing SEMA4D or IFITM1 promoted, while silencing KIF20A or GPR87 inhibited the proliferation of melanoma cells in vitro." (PMID 34659201, 2021). "To test this, we exploited the well established B16 melanoma model, which is syngenic with the C57BL6 background of our mutants, and that we found to produce Sema4D." (PMID 17519029, 2007). "Bioinformatics analysis revealed that Sema4D is involved in the PI3K/AKT signaling pathway which is activated and plays important roles such as being involved in the development and occurrence in melanoma and it also activate receptor tyrosine kinases." (PMID 37096066, 2023). "In specific, the results of our in vitro experiments suggest that SEMA4D and IFITM1 may function as tumor suppressor genes while KIF20A and GPR87 may function as oncogenes in melanoma." (PMID 34659201, 2021). "In this study, we present the first evidence that SEMA4D, IFITM1, KIF20A and GPR87 may possess a prognostic value for melanoma." (PMID 34659201, 2021).
melanoma (continued). "Finally, SEMA4D and IFITM1 may function as tumor suppressor genes, while KIF20A and GPR87 may function as oncogenes in melanoma as revealed from results of in vitro experiments." (PMID 34659201, 2021).
pancreatic cancer (7 papers, 2016 to 2024). "Kato reported the cells expressing Sema4D in the tumor stroma of pancreatic cancer to be tumor-infiltrating lymphocytes(mainly T cells and B cells)." (PMID 27456345, 2016). "Similarly, SEMA4D has also been studied to understand its role in various human malignancies, including breast, colon and pancreatic cancer." (PMID 38544823, 2024). "Notably, SEMA4D is overexpressed in various malignancies compared with normal tissue cells, such as prostate cancer, pancreatic cancer, cervical cancer, and particularly CRC." (PMID 34337054, 2021). "Clinical study, NCT03373188 is a randomized phase I trial evaluating the efficacy of anti-semaphorin 4D (anti-SEMA4D) monoclonal antibody VX15/2503 with and without ipilimumab or nivolumab in treating patients with stage I-III pancreatic cancer that is resectable or locally advanced." (PMID 32748119, 2020).
prostate carcinoma (7 papers, 2012 to 2024). A carcinoma that arises from epithelial cells of the prostate gland. "PlexinB1 and its ligands, Sema4D and Sema3C, are associated with tumor progression and bad prognosis of many tumor types, including breast, ovarian, glioma, and melanoma as well as prostate cancer." (PMID 31861264, 2019). "A similar decrease in RanGTP levels was also found in the prostate cancer cell line, LNCaP, upon Sema4D treatment." (PMID 37563360, 2023). "Treatment of 22Rv1 prostate cancer cells with Sema4D or dihydrotestosterone (an AR agonist) resulted in a significant increase in endogenous AR in the nucleus, compared to vehicle control." (PMID 31861264, 2019). "We show here that activation of PlexinB1 by Sema4D and Sema3C results in translocation of endogenous GR to the nucleus in prostate cancer cells, and that this effect is dependent on PlexinB1 expression." (PMID 31861264, 2019). "PlexinB1, Sema4D, and Sema3C are overexpressed in prostate tumors and expression of Sema3C is an independent predictor of biochemical recurrence of prostate cancer." (PMID 31861264, 2019). "Sema4D/Plexin-B1 increased the proliferative and invasive potential of LNCaP prostate cancer cells through the activation of ErbB2 and Akt, but decreased the motility and proliferation of PC3 prostate cells." (PMID 29971044, 2018). "In whole-blood RNA, Sema4D was identified as one of six RNAs strongly predicting shorter survival among patients with castrate-resistant prostate cancer." (PMID 29971044, 2018). "Blocking Sema4D/4C-PlexinB1/B2 signalling may therefore be of benefit to the treatment of ADT resistance in late-stage prostate cancer." (PMID 37563360, 2023). "This hypothesis is consistent with our in vitro findings: knockdown of Plexin-B1 reduces migration and invasion in prostate cancer cells expressing ErbB2, while activation of endogenous Plexin-B1 with Sema4D promotes migration and invasion." (PMID 36936664, 2023). "Moreover, SEMA4D is elevated in a variety of tumor tissues relative to normal tissue cells, including breast, cervical, epithelial ovarian, and prostate cancers as well as CRC." (PMID 34337054, 2021). "While no Sema4D mutation has been reported in human cancers, Plexin-B1 mutations and copy number changes are noted commonly in various cancers, including melanomas, pancreas, breast, and prostate cancers." (PMID 29971044, 2018). "DU145 and PC3 prostate cancer cells (both AR negative and GR positive) were serum-starved and then treated with Sema4D (2 μg/mL), dexamethasone (10 nM) or vehicle for 60 min." (PMID 31861264, 2019). "Prostate cancer cells PC3, which lack endogenous AR, were transfected with AR-Flag together with Sema4D-Fc or vector-Fc, with or without WT or non-functional mutant forms of Ran—RanQ69L or T24N." (PMID 37563360, 2023).
glioma (6 papers, 2008 to 2024). A benign or malignant brain and spinal cord tumor that arises from glial cells (astrocytes, oligodendrocytes, ependymal cells). "SEMA4D and FAK are associated with poorer prognosis in high-grade gliomas." (PMID 39513861, 2024). "Except for GABBR1 and SEMA4D, other genes are upregulated in glioma tissues." (PMID 37488455, 2023). "In recent studies, TAM-derived factor (SEMA4D) has been shown to promote pericyte recruitment in neovascularization and cellular communication between glioma stem cell-derived perivascular cells and ECs, thus directly contributing to vascular stability in gliomas." (PMID 36474171, 2022). "In this study, we analysed the expressions of seven semaphorins of class-3, SEMA4D, VEGF and the NRP1 and NRP2 receptors in 38 adult glial tumours." (PMID 18781179, 2008). "We studied by quantitative real-time RT–PCR the expression of the seven semaphorins from class-3 (A-G), SEMA4D, NRP1, NRP2 and VEGF in 11 adult low-grade and 27 high-grade gliomas." (PMID 18781179, 2008). "In this study, we analysed mRNA expression of class-3 semaphorins, in addition to SEMA4D, VEGF, NRP1 and NRP2 expressions, in 38 adult glial tumours." (PMID 18781179, 2008). "For the other studied genes (SEMA3A, B, C, E, F, G, NRP1, NRP2 and SEMA4D), we did not observe statistical difference between low- and high-grade gliomas." (PMID 18781179, 2008).
HIV-1 infection (6 papers, 2013 to 2023). The type species of lentivirus and the etiologic agent of acquired immunodeficiency syndrome (AIDS). "previously reported that SEMA4D was associated with T-cell exhaustion during HIV-1 infection, which coincides with our results." (PMID 37287907, 2023). "Loss of Sema4D/CD100 expression plays key roles in dysfunctional immunity during HIV-1 infection." (PMID 28222782, 2017). "For example, the transcripts of DHRS2 and SEMA4D were fused to upstream LTR12D and LTR12C sequences, respectively, and upregulated upon HIV-1 infection." (PMID 33021676, 2020).
liver fibrosis (6 papers, 2020 to 2025). "This study contributes to further understanding of the molecular mechanisms underlying Schistosoma-host interactions, and Sema4D may be a potential target for schistosomiasis liver fibrosis treatment." (PMID 32944173, 2020). "We believe these results contribute to further understanding the molecular mechanisms underlying Schistosoma–host interactions, and Sema4D may be a potential target for schistosomiasis liver fibrosis treatment." (PMID 32944173, 2020). "Sema4D has recently been found to be highly expressed in human fibrotic livers and in mouse models of liver fibrosis." (PMID 38396409, 2024). "Using different mouse models, they demonstrated that Sema4D knockout suppresses liver fibrosis, which is partly mediated by regulating the balance of Th1, Th2, Th17 and T-bet positive Treg cells." (PMID 38396409, 2024). "Another schistosome egg-derived miRNA-71a targets semaphorin 4D(Sema4D) to play an inhibitory role in liver fibrosis." (PMID 36389166, 2022). "Our findings show that Sja-miR-71a inhibits HSCs activation to alleviate liver fibrosis by inhibiting Sema4D." (PMID 32944173, 2020). "In summary, our data show that Sja-miR-71a in S. japonicum egg-derived EVs suppresses liver fibrosis in schistosomiasis by directly targeting Sema4D." (PMID 32944173, 2020). "To further evaluate the molecular mechanisms of Sja-miR-71a in liver fibrosis, we aimed to identify direct target genes that might be controlled by Sja-miR-71a and identified Sema4D as a direct target of Sja-miR-71a." (PMID 32944173, 2020). "Next, we verified whether Sja-miR-71a suppresses liver fibrosis through the Sema4D/TGF-β1 axis and Sema4D/IL-13 axis in HSCs." (PMID 32944173, 2020). "Thus, we conclude that Sja-miR-71a suppresses liver fibrosis by inhibiting the Sema4D/TGF-β1 and Sema4D/IL-13 axes." (PMID 32944173, 2020). "Next, we tested whether Sja-miR-71a inhibits HSCs activation to alleviate liver fibrosis by inhibiting Sema4D." (PMID 32944173, 2020). "Sja-miR-71a suppresses liver fibrosis by Sema4D/TGF-β1 axis and Sema4D/IL-13 axis." (PMID 32944173, 2020). "Thus, we concluded that Sja-miR-71a suppression of liver fibrosis is partly mediated by regulating the balance of Th1, Th2, Th17 and Treg cells via inhibiting Sema4D." (PMID 32944173, 2020). "In addition, Sja-miR-71a suppression of liver fibrosis is partly mediated by regulating Th1, Th2, Th17 and Treg balance via inhibiting Sema4D." (PMID 32944173, 2020). "Thus, we concluded that Sja-miR-71a-based suppression of liver fibrosis is partly mediated by regulating the Th1/Th2/Th17/Treg balance by inhibition of Sema4D." (PMID 32944173, 2020). "Exosomal Sja-miR-71a from S. japonicum eggs targets Semaphorin 4D (Sema4D), thereby inhibiting the TGF-β1/SMAD and IL-13/STAT6 pathways and regulating the Th1/Th2/Th17 and Treg balances to inhibit liver fibrosis." (PMID 39204224, 2024). "Therefore, we speculated that Sja-miR-71a suppresses liver fibrosis through the Sema4D/TGF-β1 and Sema4D/IL-13 axes." (PMID 32944173, 2020).
experimental autoimmune encephalomyelitis (5 papers, 2022 to 2025). An autoimmune demyelinating disease of the central nervous system that is produced experimentally in animals by the injection of homogenized brain or spinal cord in Freund's adjuvant. "Upregulation of SEMA4D following spinal cord injury has been reported, and interactions between SEMA4D and PLXN-B1 and -B2 receptors have been implicated in neuroinflammation and pathogenesis of experimental autoimmune encephalomyelitis." (PMID 35933420, 2022).
heart failure (5 papers, 2013 to 2025). Inability of the heart to pump blood at an adequate rate to meet tissue metabolic requirements. "The results showed a significant increase in plasma Sema4D levels in HF patients with the highest levels being in patients with both heart failure and diabetes." (PMID 23741311, 2013). "Our findings should encourage future studies in animal models and with larger cohorts of patients to understand the role of Sema4D in heart failure and diabetes." (PMID 23741311, 2013). "Notably, increased levels of circulating Sema4D have been observed in patients with heart failure, strongly supporting its feasibility as a clinical biomarker." (PMID 40507881, 2025). "Increased levels of both soluble and membrane-bound Sema4D were reported in serum and on T cells in patients with heart failure, where inflammation plays a significant role in pathogenesis and where Sema4D has been shown to participate in platelet activation as well as in thrombus formation in vivo." (PMID 30134791, 2018).